IL10 (interleukin 10)
Diseases named in the same sentence as IL10 in open-access papers (continued):
Sharing a sentence is not in itself a finding about the gene and the disease.
tumor (continued). "It is thought that IL-10 deficiency leads to elevated levels of TNF-α, IL-6, and IL-17, which in turn allow persistence of chronic inflammation thus promoting tumor growth." (PMID 24639678, 2014). "The induction of IL-10 by TLR agonists has been demonstrated in infectious disease setting as well as tumor setting." (PMID 24624132, 2014). "Tumor-associated dendritic cells (TADCs) are important in tumor immune surveillance, and it has been reported that the secretion of interleukin (IL)-10 by cancer cells is a major factor involved in the induction of TADCs in the tumor microenvironment." (PMID 25013476, 2014). "PGE2 has also been shown to induce the production of IL-10 and directly suppress the production of proinflammatory cytokines by CD4+ T cells, implicating it as a key player in tumor-associated immunosuppression." (PMID 24698959, 2014). "The secretion of IL-10 by immune and malignant cells, as induced by the E6 protein of human papilloma virus type 16 or 18, contributed to tumor progression by upregulating CIP2A and MYC." (PMID 25015035, 2014). "On the other hand, in advanced stages, TAMs release cytokines such as transforming growth factors β1 (TGF β1) and IL-10 and promote tumour development through inhibition of anticancer immune responses." (PMID 25126569, 2014). "By influence of immune suppression, regulatory T cells and tumor cell limit functions of other T cells by cytokine IL-10 and TGF-β." (PMID 25140193, 2014). "Irrespective of the source, the self-antigen specific role of IL-10 reported in this paper supports IL-10 inhibition as a way of improving the efficacy of vaccines against self-antigens that are candidate tumor antigens." (PMID 24596571, 2014). "In the present paper, we develop a mathematical model that describes the anti-tumor activity of CD8+ T cells in terms of IFN- and IL-10 productions, when these T cells are activated by IL-27 from the tumor microenvironment." (PMID 24633175, 2014). "Altogether these publications suggest IL-10 induction is probably a common regulatory mechanism that dampens TLR agonists-induced anti-tumor immunity." (PMID 24624132, 2014). "The cytokine's secretion controls the immune and inflammatory environment to either favor antitumor immunity or enhance tumor progression through IL10, TGFβ, IL6, IL17, or IL23." (PMID 25525301, 2014). "A number of human cells produce IL-10, including the specific T cell subsets, Th2, Tr1, Tc2, macrophages, monocytes, mast cells, liver cells and tumor cells." (PMID 24270972, 2014). "Originally defined by secretion of IL-2 or IL-10, which in turn activates Th1 or Th2 cells, now the concepts of M1/M2 subtypes basically represent tumor suppressive or tumor supportive macrophages, albeit a little bit oversimplified." (PMID 24675569, 2014). "Presistence of pNGVL3-mIL-12 plasmid in the tumor microenvironment can explain the partial inhibition of IL-10 expression and the therapeutic effect on tumor growth at 21 days." (PMID 24808638, 2014). "Macrophages activated by IL-4, IL-13, and IL-10 are referred to as M2 macrophages, which can suppress inflammation, induce angiogenesis, promote tissue repair, and enhance tumor growth." (PMID 24580730, 2014). "IL-10 is an important immunosuppressive cytokine detected in many cancer patients and has the ability to modulate anti-tumour immunity." (PMID 24520352, 2014). "The tumour however, limits immune activation by secreting immune inhibitory cytokines such as IL-10, and tumour growth factor (TGF)-β as well as inducing regulatory cell populations including myeloid derived suppressor cells (MDSCs) and regulatory T cells." (PMID 24957270, 2014). "Tregs in the tumor microenvironment produce anti-inflammatory cytokines such as IL-10 and TGF-β that impair T cell responses and directly inhibit the function of APCs through interaction with the inhibitory receptor, CTLA-4." (PMID 24860789, 2014).
tumor (continued). "Prevention of IL-10 signaling allows excessive inflammation and promotes development of Tregs and MDSCs, which inhibit anti-tumor immunity and permit tumor growth." (PMID 24670367, 2014). "Expression of angiopoietin-2 by tumor cells induces the recruitment of Tie-2-expressing monocytes in the tumor and the release of IL-10 by the cells." (PMID 24765614, 2014). "Switching of tumor-infiltrating macrophages from M2 to M1 has been reported upon use of a combination of CpG ODN and anti-IL-10 antibodies to suppress tumor growth." (PMID 24642245, 2014). "Simulations of the model show how Interleukin-27 promotes CD8+ T cells to secrete Interleukin-10 to inhibit tumor growth." (PMID 24633175, 2014). "Release of ROS has the ability to inhibit myeloid derived suppressor cell (MDSC) maturation, known to suppress immune responses against tumors by releasing IL-10, and induce cell death of tumor cells in the established tumor." (PMID 24949488, 2014). "Based on the ratios of the stimulatory-to-regulatory gene transcripts (ratios of both T-bet/FoxP3 and IFN-γ/IL-10), we concluded that combined treatment fostered a local immuno-activating tumor microenvironment." (PMID 24586709, 2014). "ROS production by MDSC is sustained by the inflammatory tumor microenvironment, enriched, among others, in IL-10, IL-6, and TGF-beta, as well as by the cell-to-cell contact with lymphocytes." (PMID 25538892, 2014). "The suppression of TNF-α function favours tumour proliferation and differentiation through the activation of IL-10." (PMID 26316944, 2014). "In response to cytokines such as TGF-β, IL-10, and macrophage colony-stimulating factor (M-CSF), TAMs can promote tumor proliferation and progression and stroma deposition, while also contributing to the remodeling and inhibition of adaptive immunity." (PMID 24578639, 2014). "IL-10 secretion by tumor cells was previously demonstrated as a key factor contributing to M2 polarization." (PMID 25526031, 2014). "Tumor cells use a variety of different pathways to achieve this goal including overexpression of certain cytokines (IL-4, IL-10, TGFB), catabolic enzymes such as indoleamine 2,3 dioxygenase, and also by upregulation of surface PD-L1 expression." (PMID 24551119, 2014). "TAM accumulating at tumor sites exhibit immunosuppressive activity by expressing high levels of interleukin 10 and programmed death ligand 1, and promote angiogenesis by producing metalloelastase and VEGF." (PMID 25303284, 2014). "The expression of ILT4 and IL-10 in 117 primary tumor specimens was determined by immunohistochemistry." (PMID 24762057, 2014). "Tumor cell supernatants (CM) induced macrophages towards a M2 prone phenotype with relatively high expression levels of the M2 cytokine IL-10 and low mRNA levels of the M1 markers IL-12, CD80 and HLA-DR." (PMID 25192022, 2014). "In most patients, both PBMC and TIL responses to LMP1 were characterized by IL10 secretion; this highlights the crucial role of IL10-secreting cells in favoring tumor immune evasion in EBV-positive HL patients." (PMID 25525301, 2014). "By secreting cytokines such as IL-6 and IL-10, HNSCC tumor cells promote a Th2-skewed response, which is associated with decreased antitumor efficacy." (PMID 24698959, 2014). "On the other hand, tumor cells have been shown to inhibit DC maturation through the secretion of IL-10." (PMID 25254213, 2014). "Conversely, IL-10 has been identified as a potential inhibitor of proinflammatory cytokines and other cytotoxic molecules that mediates the killing of tumour cells." (PMID 26316944, 2014). "IL-10 blockade using anti-IL-10 neutralizing mAb significantly enhanced the anti-tumor effects of topical imiquimod." (PMID 24624132, 2014). "The results of the present study revealed that activated STAT-3 stimulated the injured liver cells to secrete VEGF and IL-10 to affect the differentiation and maturation of DCs, and thereby inhibited the immune response, allowing the tumor cells to escape it." (PMID 25009646, 2014).
tumor (continued). "IL-10 also blocks the development of regulatory T cells (Tregs) and Myeloid-derived suppressor cells (MDSCs), which are inhibitors of anti-tumor immunity." (PMID 24670367, 2014). "MDSC have also been shown to impair innate immunity by their cross-talk with macrophages, which increases MDSC production of IL-10 and decreases macrophage production of IL-12, converting anti-tumor M1 cells into M2 cells that enhance tumor progression." (PMID 23508517, 2013). "Next, to assess the immunogenicity of ethanol-treated tumor cells, the production of immune-suppressive cytokines such as the active form of TGF-β1, VEGF, and IL-10 in tumor cells was analyzed." (PMID 23717436, 2013). "These cells are induced in the periphery or at tissue/tumor sites from the naïve CD4+CD25(−) T cells in the presence of IL-10 or TGF-β and exert suppression by the production of soluble suppressor factors." (PMID 23898333, 2013). "Despite these data, little information is available about the roles of Treg-derived IL-10 in tumor microenvironments." (PMID 23986759, 2013). "Several recent studies have suggested that IL-10 plays a role in inhibiting tumor development, growth, and metastases." (PMID 23533029, 2013). "Many tumor-derived factors, such as IL-10, IL-6 and VEGF that are crucial for both tumor growth and immunosuppression, activate STAT3 to create an efficient “feed-forward” loop to induce persistent STAT3 activity in tumor cells and the tumor microenvironment." (PMID 24324713, 2013). "IL-10 produced by tumor macrophages induces a regulatory phenotype in T cells and an escape mechanism of the immune response that facilitates tumor growth." (PMID 23936772, 2013). "Solid tumors are frequently infiltrated by tumor-associated macrophages (TAMs), which are driven by tumor and T cell derived cytokines (especially IL-4, IL-10, and IL-13) to acquire an “alternatively activated” M2 phenotype with pro-tumor properties." (PMID 23950747, 2013). "These TAM are then able to contribute to the suppressive tumor microenvironment, expressing high levels of suppressive cytokines (such as TGF-β and IL-10), promoting tumor angiogenesis, and inhibiting anti-tumor immunity." (PMID 23653893, 2013). "Collectively these studies in both the animal and human systems suggests that IL-10 is involved in both direct and indirect tumor immunosuppressive networks that can promote and facilitate tumor immune tolerance resulting in malignant progression." (PMID 23533029, 2013). "We also found that the tumor size is correlated strongly with IL-6 and IL-10 levels (r = 0.925, P < 0.001; r = 0.821, P < 0.001), respectively.Conclusion." (PMID 27335826, 2013). "A similar observation has been described in mice, where the presence of a subcutaneous tumor resulted in a DC-to-macrophage shift, with macrophage-like cells producing immune-suppressive factors such as IL-10, iNOS, and Arginase." (PMID 24324467, 2013). "TGF-β1 has been demonstrated to suppress INF-γ production by CD8+ T cells and to promote, in concert with IL-6, IL-1β, and IL-10, Treg generation, and Th17 differentiation, thus favoring tumor growth and progression." (PMID 23533994, 2013). "Our results indicated a potential role for IL-6, and IL-10 as a tumor marker for HCC with respect to AFP and this was in agreement with the previous studies." (PMID 27335826, 2013). "Differentiation of naïve CD4+ T cells into iTreg cells in the periphery is encouraged by tumor antigen in the presence of certain cytokines such as IL-2, IL-10, and TGF-β." (PMID 23378947, 2013). "Signaling through TLRs 1, 2, or 6 causes DCs to produce IL-10, which in turn promotes T-cell development towards regulatory or TH2 phenotypes incapable of promoting anti-tumor immune responses." (PMID 24829749, 2013). "IL-10 is highly regarded as an immunosuppressive cytokine and plays a role as the mediator of tumor regression." (PMID 24358317, 2013).
tumor (continued). "IL-27 has also been shown to enhance IL-10 production and negatively regulate IL-4 and IL-17, however, subtle effects of Il27ra genotype were observed for these cytokines in the tumor models." (PMID 23554861, 2013). "The importance of IL-10 in regulating immune cell function is further illustrated by the fact that many tumour cells and intracellular pathogens produce or elicit production of IL-10 to enhance survival." (PMID 23951138, 2013). "For example, transfection of tumor cells with IL-10 or systemic administration of exogenous IL-10 significantly suppressed tumor growth and led to tumor rejection in several different murine tumor models in vivo." (PMID 23533029, 2013). "Mutations within tumors can play a role in this process; BRAF mutations drive tumor cells to produce pro-inflammatory cytokines like VEGF, IL-10, and IL-6, while at the same time decreasing expression of anti-tumor cytokines such as IL-12." (PMID 24829749, 2013). "Our data suggest overriding immune suppressive effects of IL-10 in tumor-conditioned skin and argue in favor of the incorporation of GM-CSF and IL-4 in adjuvants for transcutaneously or intradermally delivered cancer vaccines." (PMID 23875023, 2013). "Level of TGF-β and IL-10 significantly declined accompanied by an elevation of IFN-γ in the serum of orlistat-administered tumor-bearing mice compared to respective controls." (PMID 24349275, 2013). "Previously, we have demonstrated that blocking STAT3 signaling in the APCs by specific inhibitors resulted in reduced IL-10 expression and reversal of hMSC and tumor cell-mediated inhibition of proinflammatory cytokines." (PMID 24073274, 2013). "This pivotal role, associated with the finding that the tumor environment is usually rich in IL-10 secreted by tumor cells and/or by tumor infiltrating elements, suggests that this cytokine has a critical function in tumor immune escaping." (PMID 23663506, 2013). "Granzyme B, whose secretion by PDC is boosted by tumor-derived IL-3 and IL-10, is involved in the downregulation of the CD3ζ chain of T effector cells, thereby resulting in their anergy or deletion by apoptosis induction." (PMID 24348482, 2013). "Results from preclinical and clinical studies have established IL-24, a member of the IL-10 super-family, functions as a tumor suppressor/cytokine gene." (PMID 24377906, 2013). "IL-10 is generally expressed at high levels in the microenvironment of metastatic melanoma and can either be directly derived from tumor cells or from infiltrating immune cells." (PMID 24324467, 2013). "IL-10-mediated prevention of tumor growth is dependent on T cells and/or NK cells as these effects are abrogated in immunodeficient mice." (PMID 23755052, 2013). "Correlation analysis revealed significant positive correlations between tumor TL and peripheral levels of three cytokines (IL-7, IL-8 and IL-10)." (PMID 23383336, 2013). "Recently, it has been proposed that IL-10 plays a key role in the oncogenetic and metastatic ability of neoplasms." (PMID 27335826, 2013). "Human CD4+CD25neg T cells and autologous immature dendritic cells (iDC) were co-incubated with irradiated tumor cells and a cytokine mix containing IL-2, IL-10, and IL-15 (20 IU/mL of each) for 10 days at 37 °C." (PMID 23898333, 2013). "In general, we found that the entire family of IL-10 cytokines including IL-10, IL-19, IL-20, IL-22 and IL-24 was increased in tumor compared to normal skin." (PMID 23667456, 2013). "Perhaps, most of the Tr1 cells in the periphery exist in precursor form and are only expanded at tumor site where antigen is ubiquitous and key cytokines such as IL-10 are abundant, similar to the in vitro simulations." (PMID 23874336, 2013). "This stimulatory effect is appreciated despite the fact that the tumor environment is composed largely of the immunosuppressive cytokines IL-10 and TGF-β." (PMID 23606870, 2013).
tumor (continued). "This choice derives from our previous observation related to the presence within tumors of IL-10-secreting Treg able to strongly impair anti-tumor immune response." (PMID 23663506, 2013). "Tumor cells produce factors such as interleukin-10, transforming growth factor-β1 and vascular endothelial growth factor (VEGF) that suppress the function of immune cells or induce apoptosis of immune cells." (PMID 23596479, 2013). "From a panel of tumor-associated suppressive factors (including PGE2), we found only IL-6 and IL-10 to induce STAT3 phosphorylation during human MoDC development." (PMID 24324467, 2013). "More importantly, when peptide-pulsed DC vaccination and IL-10 blockade were applied in a combinatorial protocol, complete abrogation of tumor growth was achieved in 100% of treated mice." (PMID 23663506, 2013). "Alternatively, a neutralizing anti-IL-10 monoclonal antibody (mAb) was subcutaneously administered at the site of tumor challenge to counteract regulatory cells." (PMID 23663506, 2013). "In TME, we detected a higher level of IL-12 and IFN-γ (enhancing anti-tumor immunity) and lower level of TGF-β1 and IL-10 (suppressing anti-tumor immunity) in both treated groups." (PMID 24304581, 2013). "Although IL-10 is generally regarded as an anti-inflammatory and immunosuppressive cytokine that favors tumor escape from immune surveillance, evidence is accumulating that IL-10 also possesses immunomodulatory properties that support antitumor immunity." (PMID 23533029, 2013). "Sunitinib shifted tumor-infiltrating lymphocytes (TILs) in mice from releasing Th2 cytokines (IL-10, TGF-β) to Th1 cytokines (IFN-γ)." (PMID 24232460, 2013). "A recent study using an immunocompetent rat tumor model showed several changes in immunity following IRE tumor ablation, including changes in T-cell subset percentage, cytokine-positive splenocytes, and serum sIL-2R and IL-10 levels in peripheral blood." (PMID 23717630, 2013). "In HCC patients tumor size was correlated strongly with IL-6 and IL-10 levels (r = 0.925, P = 0.001; r = 0.821, P = 0.001), respectively." (PMID 27335826, 2013). "In tumor tissue, IL-10 has both immunosuppressive properties (potentially cancer promoting due to inhibitory effects on antigen presenting capacity) and anti-angiogenic properties (potentially cancer inhibiting)." (PMID 22353218, 2012). "More specifically, IL-6 and IL-10 collectively promote growth of KSHV-infected tumor cells, angiogenesis and suppression of T-cell activation." (PMID 22505930, 2012). "MSC2 treatment groups also had elevated levels of secreted IL1RA, IL10 and most chemokines tested, which suggests a net tumor supportive immunosuppressive effect by this treatment group." (PMID 23029122, 2012). "IL-10 is a Th2-type pleiotropic cytokine that is produced at the tumour site and is increased in sera of patients suffering from different cancer types." (PMID 22220169, 2012). "A recent study found that MDSCs can impair tumor immunity not only by suppressing T-cell activation but also by interacting with macrophages to increase IL-10 and decrease IL-12 production, thereby promoting a tumor-promoting type 2 response." (PMID 22481970, 2012). "For IL-10, the stromal expression was highest in the primary tumors (P < 0.001), whereas in the metastases the expression was highest in tumor cell areas (P < 0.001)." (PMID 22353218, 2012). "By contrast, IL-10 feeds back on macrophages to increase alternative macrophage differentiation, and the progressive induction of IL-10 in tumor infiltrating cells during tumor growth has been shown to suppress anti-tumor adaptive immune responses." (PMID 22761754, 2012). "Conversely, M2 macrophages always express the scavenger receptor (SR), the mannose receptor (MR), and IL-10, which lead M2 macrophages to mainly participate in parasite clearance, tissue remodeling, immune modulation, and tumor progression." (PMID 22778768, 2012).